IFNG (interferon gamma)
Diseases named in the same sentence as IFNG in open-access papers (continued):
Sharing a sentence is not in itself a finding about the gene and the disease.
tumor (continued). "Increasing IFNG production (kc1) slightly reduced tumor size (median for kc1: 86 mm2 vs. unmodified ACT of gp100 T cells: 92 mm2, p-value < 0.001) while the other two parameters had essentially no impact on tumor size (median for kd5a: 92 mm2 and kp3a: 91 mm2, p-values vs. unmodified both > 0.05)." (PMID 28101055, 2016). "Finally, we could show that inhibition of tumor metastasis required antigen-specific CD8 T cells and IFNγ, but not perforin." (PMID 24498205, 2014). "However, the therapeutic application of the complex did not suppress metastasis because the complex could not reverse tumor cell-induced STAT3 activation and neither activate IFNγ/STAT1 signaling and autophagy." (PMID 21931823, 2011). "Additionally, this study explored the role of interferon-gamma (IFN-γ) and its receptor (IFN-γ-R1) in combination with SB treatment, revealing that, although IFN-γ-R1 expression was increased, IFN-γ did not affect the efficacy of SB in reducing tumor cell viability." (PMID 38650948, 2024). "In the enzyme-linked immunosorbent spot (ELISPOT) experiment, small amounts of IFNγ spots in non-OVA peptide-treated lymphocytes may be attributed to nonspecific activation of CTLs in the periphery that ultimately circulate to the tumor and thus tumor-draining lymph nodes." (PMID 33986267, 2021). "In order to clarify the mechanism by which hAAT may act to affect tumor-infiltrating macrophages in such a context-dependent manner, BMDMs were pretreated with hAAT and then cocultured with RMA tumor cells, with or without stimulation with recombinant IFNγ and IL-1β." (PMID 28003813, 2016). "In contrast, while the addition of IFNγ and/or TLRa without monocytes displayed varying background inhibition of MDA-MB-231-f cells, the additional inclusion of monocytes could markedly and significantly boost tumor inhibition, especially when combinations of IFNγ and/or TLRa were included." (PMID 27341020, 2016). "Besides, the addition of IFNγ in theco-culture did not induce detectable amounts of NO when the macrophages were IRF-1deficient, suggesting that in these conditions, IFNγ by itself was not able toinduce NO production neither by resident macrophages nor by L929 tumor cells." (PMID 25659093, 2015). "Also in a mouse glioblastoma model, an inhibitor of M-CSFR significantly increased survival and regressed established tumor, which was in this case not due to TAM depletion, but rather to a decreased expression of M2 markers and an unopposed production of anti-tumoral GM-CSF and IFNγ." (PMID 24723924, 2014).
infection (8,265 papers, 2002 to 2026). The state of being infected such as from the introduction of a foreign agent such as serum, vaccine, antigenic substance or organism. "As expected, volcano plots showed that most genes associated with the pathways linked to immune responses including “Interferon gamma, Interferon alpha and Complement” were upregulated by the infection." (PMID 39883714, 2025). "As a control group to track OT-I T cells longitudinally, we used ΔActA-Lm-OVA, as the loss of host IFNγ impairs the ability of mice to clear wild-type Lm-OVA infection." (PMID 40163479, 2025). "Mutations in the host's interferon-gamma (IFN-γ) pathway enhance the risk of infection due to M. avium and M. abscessus." (PMID 40264600, 2025). "IP-10 was the only biomarker weakly associated with recovery status in the full model, and IFNγ was weakly associated with PASC resolution in those with a more recent infection." (PMID 40449327, 2025). "IFNγ- and Rag1- deficient mice both showed a 100% mortality rate by 64- and 93-days post infection, respectively, demonstrating that type 1 immunity and adaptive lymphocytes in general are required for protection." (PMID 40568097, 2025). "Gene expression of pro-inflammatory cytokines IL-1β, IL-2, IL-4, and IL-6, as well as IFNγ was significantly upregulated in nasal turbinates in response to infection with all VOCs, with the Gamma variant inducing the highest inflammatory response." (PMID 40295859, 2025). "To understand the influence of Tr1 cells on the systemic response to infection, we quantified the abundance of Tr1-associated molecules (granzyme A, IFNγ, IL-10, and LAG3) in plasma from the same blood samples used to study CD4+ T cells as a part of MUSICAL." (PMID 41000872, 2025). "Separating individuals with TBI based on time since likely Mtb exposure revealed that more recent infection was associated with reduced IFNγ responses and a higher proportion of IL-2/TNF-secreting cells." (PMID 41159744, 2025). "The main side effect of inhibitors of JAK1 and JAK2 can be an increased risk of infection, related to a depressed Th1 response and a reduced production of interferon-gamma (INF-γ)." (PMID 39100065, 2024). "Together, these results suggest that genetic, environmental and individual immune variation as it relates to differential levels of type 1 immune responses and IFNγ is associated with varied infection burden." (PMID 38877178, 2024). "Canine leishmaniosis (CanL) is a zoonotic disease caused by Leishmania infantum, where increased interferon-gamma (IFN-γ) levels are associated with controlling the infection and mild to moderate disease." (PMID 39682429, 2024). "It is known that IL32γ and IFNγ play a role in infection control, but they exacerbate the responses linked to tissue damage present in ML." (PMID 39844838, 2024). "Concerning the analysis of the CD4+ T lymphocyte count, there was an association only for rs2069705 (IFNG) directed to the group of individuals with HIV mono-infection (G2)." (PMID 39066175, 2024). "Similar to Ifne-/- mice, NK cell deficient Il15-/- mice have reduced IFNγ responses during infection and rIFNε is unable to induce IFNγ responses or protect against infection in NK cell-deficient Il15-/- mice." (PMID 38263527, 2024). "Transgenic mice that lack the cytotoxic T cell potential (C57Bl/6 Perforin -/-) have been shown to demonstrate increased susceptibility and lethality to R. australis (TRG) infection compared with both wild-type (WT) and IFNγ knock out (KO) mice." (PMID 38567021, 2024). "In the current study, we have found that the premature egress phenotype in HFFs, triggered by IFNγ following infection, is tightly linked with host cell death." (PMID 39292011, 2024). "We identified 163 SNPs, 72 QTLs, 197 candidate genes, and 8 miRNAs associated with high IFNγ production in response to Mb infection." (PMID 38892353, 2024).
infection (continued). "Our findings are novel in that they extend these observations of IFNγ-mediated protection from infection in KC to a poxvirus (VV) and investigate viral susceptibility in the context of JAKi exposure." (PMID 37298195, 2023). "Macrophages acquire a pro-inflammatory M1 phenotype under the action of various infection- and damage-associated factors, such as LPS, TNFα, and IFNγ." (PMID 38069411, 2023). "Given the importance of IFNγ in our predictive analysis and the association between IL-9 and survival, we analysed the kinetics of IFNγ/IL-9 ratio at the onset of infection." (PMID 37569646, 2023). "In examination of mice deficient in CD8 effector functions, infection of IFNγ deficient (Ifng−/−) and perforin deficient (Prf−/−) mice but not TNFα deficient (Tnfa−/−) mice resulted in worsened disease." (PMID 37866114, 2023). "In the same way for each additional unit of IFNγ secreted after specific T cell activation, the risk of infection decreases by 73.5% (p = 0.04)." (PMID 37606852, 2023). "TEFF cells produce large quantities of pathogenic cytokines (IFNγ and TNFα) and lytic molecules that contribute to organ damage during severe infections." (PMID 37426662, 2023). "Increased CD4+ cells in the lungs of MFD-fed mice during acute and chronic stages of infection likely caused the elevated levels of IFNγ and initiated host survival mechanisms." (PMID 36676177, 2023). "In septic patients, low IFNγ-secretion is linked to secondary infection or death, while IFNγ-treatment increases HLA-DR expression and production of pro-inflammatory cytokines." (PMID 38057824, 2023). "A study using a mouse model revealed that IFNγ-producing γδ T cells play a pathogenic role that is strictly dependent on the liver stage of infection, and affecting disease severity." (PMID 38124746, 2023). "Interferon responses, including type I IFN and IFNγ, have been associated with the suppression of liver-stage infection in mice." (PMID 37195999, 2023). "More recently, higher whole-blood interferon gamma (IFNγ) responses to SARS-CoV-2 peptides among individuals who had received at least one vaccine dose were associated with a lower risk of breakthrough infection over the subsequent 6 mo period." (PMID 37655880, 2023). "The combination of high anti-S IgG responses and high S-specific IFNγ responses was associated with a lower frequency of breakthrough infection." (PMID 37655880, 2023). "An increase in the frequency of CD4+IFNγ+ T cells was observed at the site of infection both in mice genetically deficient for c-MET in neutrophils and in the lesion of mice treated with the c-MET inhibitor capmatinib." (PMID 35041723, 2022). "This increase in T‐bet is strikingly different to the changes in Th1 response in neonatal mice to Listeria, an infection that causes strong Th1 commitment, but where T‐bet and IFNγ were down in pup splenocytes by real time PCR." (PMID 36131528, 2022). "IL-2, IL-5, IL-17F, IFNγ and TNFα inductions were positively associated with the infection status in the N-peptides restimulated cells (308%, 65%, 39%, 304% and 40% increase when infected, respectively, FDR < 0.1)." (PMID 35313592, 2022). "Corroborating the previous analysis, IL4 rs2070874*T and IFNG rs2069727*G were significantly associated with infection in a logistic regression model after adjusting for the confounders of age, sex and village." (PMID 35759449, 2022). "We further showed that suppression of viremia and virus dissemination are dependent on Plasmodium-induced IFNγ and are associated with reduced infection of CD45− cells at the site of virus inoculation." (PMID 35039441, 2022). "Experimentally, metastatic CL can be mimicked upon infection of the interferon gamma (IFN-γ)-deficient mice (Ifng−/−) with Lgy-bearing LRV1 (LgyLRV1+), which induces a severe metastatic phenotype." (PMID 36034709, 2022).
infection (continued). "Other genes, including neutrophil cytosolic factor 2 (Ncf2), Toll-like receptor 4 (Tlr4), interferon gamma (Ifng), and histocompatibility complex (H2) haplotypes, have also been linked to survival after STm infections in mice (1, 12, –, 15)." (PMID 35880881, 2022). "Because nonimmune cells express IFNγ receptors and can respond to IFNγ signaling, the infection profile of these subsets was assessed in coinfected mice deficient in IFNγ." (PMID 35039441, 2022). "It has been shown that IFNγ mediates much of these associated CNS changes after infection, such as loss of GABA transporter localization, reduced expression of key synaptic components, and displacement of synapses by microglia." (PMID 35898505, 2022). "Interferon-γ (IFNγ) has previously been clinically-associated with BKPyV infection and suggested to reduce BKPyV-infection progression in renal cell cultures; therefore we investigated its potential for regulating urothelial anti-viral self-defence mechanisms." (PMID 35194151, 2022). "Lastly, we investigated the molecular mechanism underlying the increased susceptibility to infection by HCoV-OC43 in IFNG- and IFNGR1-knockout cell lines." (PMID 35897807, 2022). "STX4 and IFNγ had the most associated GO terms, highlighting the importance of these two genes in the overall immune response to pathogen infection, while SERPINE1 was associated with eight GO terms." (PMID 35510793, 2022). "Low in vitro IFNγ production has also been associated with an increased risk of infections in fragile patients." (PMID 36016305, 2022). "Pathways associated with the production and regulation of interferon-gamma (GO:0032649) were significantly enriched in the host response to B. rossi infection, especially during infection onset." (PMID 34399690, 2021). "As originally described, antigen-specific T cells become “dysfunctional” during the chronic phase of high viral load infections, with progressive loss of interleukin (IL)-2, then tumor necrosis factor alpha (TNFα), and, finally, interferon gamma (IFNγ)." (PMID 34555119, 2021). "The observation that cydAB expression peaks with the onset of the adaptive immune response in the mouse model of infection further suggests an association between T cell cytokines, such as IFNγ, and alterations in the respiratory requirements of Mtb." (PMID 34320028, 2021). "In this study, we showed a higher serum level of IFNγ in the highly susceptible AGM compared to the less susceptible RM after B. pseudomallei HBPUB10134a infection." (PMID 33571211, 2021). "Previous data has shown that the source of the infection-associated IFNγ is complex, involving NK, NKT, CD8+ and subsequently CD4+ T cells, cell populations that all decrease in size during T. b." (PMID 34200074, 2021). "CTG is a type III strain of T. gondii that is avirulent in mice and more susceptible to IFNγ-mediated restriction than other strains thus making it ideal for identifying individual ISGs which can restrict infection." (PMID 34871166, 2021). "Previous studies showed that B cell deficient mice (muMT) are extremely susceptible to primary, chronic and secondary infections, despite unimpaired levels of IFNγ." (PMID 34871323, 2021). "We detected an accentuated decrease in the number of correlations of IFNγ in the susceptible dogs after infection diagnosis." (PMID 33617528, 2021). "In fact, in susceptible dogs, the interactome analysis showed that IFNγ involvement decreased more sharply after infection diagnosis denoting its importance in controlling the parasite proliferation." (PMID 33617528, 2021). "The upregulation of TNFα, IL6, IL1β, and IFNγ was reported as inflammatory cytokines associated with the postviral infection, which played a role in the recruitment of more immune cells for defense against the virus." (PMID 34074129, 2021).
infection (continued). "In contrast, MAIT cells deficient in the production of TNF, IFNγ, or GM-CSF were unable to provide protection, with mice succumbing to infection similar to the untreated Rag2−/−γC−/− mice." (PMID 34272362, 2021). "For example, Eomes has been associated with exhaustion during the chronic phase of infection, but it is up-regulated during acute infection, favoring effector molecule production (IFNγ), IL-15Rβ, and memory development." (PMID 34555119, 2021). "Taken together, our analysis of blood transcriptomic data suggests that long-term ART in PLHIV leads to resolution of elevated type 1 IFN activity associated with untreated infection, but increased levels of T cell activation-associated IFNγ activity." (PMID 33732256, 2021). "The finding is particularly interesting especially when we analyze the literature across different pathogenic NWHs infections that show stronger pro-inflammatory cytokine profiles characterized by IFNγ, TNFα, high levels of IL-6 as well as IL-1β." (PMID 33815363, 2021). "A significant intestinal BMP2 increase was observed at 30 days of infection, and this was closely related to the intestinal IFNγ increment and neuronal loss." (PMID 33561140, 2021). "Although advantageous in the context of these infections, both IL-17 and IFNγ are highly inflammatory cytokines and can cause unwanted harm to host tissues." (PMID 33291260, 2020). "Specifically, pro-inflammatory cytokines such as LTα and IFNγ drive the development of ECM during PbA infection, as mice with either LTα or IFNγ deficiency are completely resistant to ECM." (PMID 33316929, 2020). "Secondly, C57BL/6 Perforin-/- mice where CD8+ T cells lack the cytotoxic potential showed a higher susceptibility and lethality upon infection with R. australis compared to wild-type as well as to C57BL/6 IFNγ-/- mice." (PMID 33091016, 2020). "The infection causes increased secretion of IL-1β, IL-4, IL-10, interferon gamma (IFN-γ), IP-10, and monocyte chemoattractant protein 1 (MCP-1)." (PMID 32471251, 2020). "In studies that show an association, the presence of the T allele correlates with high IFNG expression and increased resistance to infection whereas the A allele correlates with low expression." (PMID 32433683, 2020). "In particular, the production of interferon (IFN) γ by CD4+ Th1 cells is important to control Mav infection, and mice genetically deficient in IFNγ have increased susceptibility to infection." (PMID 32582196, 2020). "Despite conferring protection against RSV replication, immunopathology has been linked to IFNγ-producing CD8+T cells during primary infection and in memory responses resulting from immunization." (PMID 32849580, 2020). "Only one patient experienced an infection caused by a pathogen potentially favored by IFNγ neutralization (disseminated histoplasmosis) during emapalumab treatment; however, it resolved without sequelae with appropriate treatment." (PMID 33424859, 2020). "The pro-inflammatory cytokine, interferon gamma (IFN-γ) produced by Th1 cells was associated with regulation of cellular immunity against infection and participated in differentiation of Th1 and Th2 cells." (PMID 32120801, 2020). "Despite overall low levels of infection and epitope presentation, we observed significant IFNγ secretion in co-cultures with DCs exposed to MeVac encoding full-length ovalbumin, in contrast to unmodified MeVac." (PMID 32098134, 2020). "Further, burdens of S. pneumoniae at 4 h after infection (9 days after IAV) were ~50% lower in lungs of IFNγ or IFNGR1-deficient mice than in co-infected control mice." (PMID 32117259, 2020). "The loss of Mincle has been shown to reduce IFNγ in an infection setting and when DDA liposomes are used as a delivery system, TDB and other Mincle ligands have been shown to bias a Th1/Th17 vaccine immune response." (PMID 30873180, 2019).